INS (insulin)
Diseases named in the same sentence as INS in open-access papers (continued):
Sharing a sentence is not in itself a finding about the gene and the disease.
Hypertension (continued). "However, for hypertension and hyperglycemic conditions one may benefit more from antioxidants that promote insulin sensitivity and lowered blood pressure such as HO-1." (PMID 32903449, 2020). "Importantly, although a well-known association was reported between weight change and SBP levels, the significant associations of changes in insulin and IR indices with incident hypertension were sustained, independent of the BMI changes in this study." (PMID 31728151, 2019). "Finally, some patients with hypertension, hyperlipidemia, and atherosclerosis were enrolled in the study and they were taking appropriate drugs, such as insulin, oral hypoglycemic agents, and antihypertensive drugs, which might affect the results of the study." (PMID 31781662, 2019). "Moreover, our results were evident that lipid profile, hypertension, and risk of heart attack and ischemic stroke do not differ among groups with different methods of insulin delivery." (PMID 31461470, 2019). "Nevertheless, our data suggest that systemic IR defined by HOMAIR index alone may be heterogeneous in nature and explained by different mechanisms, including insulin action, inflammation, insulin secretion or other complex processes leading to arterial hypertension." (PMID 30913280, 2019). "Concerning NCDs, it could be seen that methyldopa (used for hypertension in pregnant women) and insulin preparations were little affordable in CHAM facilities and the private sector, with more than 7 days`work necessary to afford the full course of monthly treatment." (PMID 30753219, 2019). "Another link is the association between hypertension, insulin signaling pathway and canonical WNT signaling, where downregulation of canonical WNT signaling in the nucleus tractus solitarii correlates with an increase in phosphorylation of insulin signaling components." (PMID 31382613, 2019). "However, in aging hypertension, the ways insulin and IGF-1 influence the cardiovascular dysfunction remain unclear." (PMID 30934575, 2019). "Moreover, increased susceptibility to hypertension after STS might be caused by epigenetic marks induced by high glucose and insulin." (PMID 29882756, 2018). "Sodium retention, plasma rennin activity, angiotensinogen, angiotensin II and aldosterone values display significant increase during obesity and additionally insulin resistance and inflammation may promote an altered profile of vascular function and consequently leads to hypertension." (PMID 30526686, 2018). "According to those results, increased waistcircumference, waist-to-height ratio, fat mass, blood glucose, insulin,triglycerides, VAI, and hypertension were associated with the MUO phenotype,suggesting that the criterion applied could identify individuals with higher CVDrisk." (PMID 30484514, 2018). "In addition to common metabolic disorders shared by hypertension and T2DM, T2DM predisposes a patient to hypertension through IR, with impaired fibrinolysis and chronic inflammation, and through high insulin level, with increased arterial stiffness, vascular volume, and sympathetic tone." (PMID 30555418, 2018). "This is important because ethnic differences also exist in T2D such that blacks have high prevalence of cardiometabolic risk factors such as large WC, inflammation, lower insulin sensitivity and hypertension, with greater risk of T2D compared to non-Hispanic whites." (PMID 32153911, 2018). "Importantly, the HFD-induced changes in cardiac microcirculatory perfusion are associated with central obesity and an impaired cardiac insulin sensitivity, but not with hypertension or signs of cardiac remodeling." (PMID 26576929, 2015). "Therefore, we tested the hypothesis that in SS hypertension, the activation of NFκB inflammatory pathway by upregulation of endogenous Ang II/reactive oxygen species (ROS) impairs insulin sensitivity and insulin signaling in the skeletal muscle." (PMID 25928697, 2015). "And, as such, use of insulin itself might control essential hypertension." (PMID 24649391, 2014).
Hypertension (continued). "We also consider the link between hypertension and IR: the insulin hypothesis of hypertension." (PMID 23573411, 2013). "According to their findings, this animal model of obese hypertension demonstrated that chronic inhibition of sympathetic activity with moxonidine therapy can reduce free fatty acids and significantly improve insulin secretion, glucose disposal, and expression of key insulin signaling intermediates." (PMID 27713282, 2010). "Various opinions exist regarding whether reduction of insulin sensitivity can induce hypertension." (PMID 17903269, 2007). "In addition to the antiadipogenic and insulin sensitizing effects, another important finding of our study is that the administration of both products, separately or in combination, prevents the development of hypertension, with this effect being more evident in those animals supplemented with CTE." (PMID 41596333, 2026). "In the KNN model, the final features included PLT, uric acid, ALT, body weight, creatinine, fasting insulin, AST, age, height, BMI, total bilirubin, HDL-C, triglycerides (TG), LDL-C, sex, DM, hypertension, ALB, TC, and HbA1c." (PMID 40361915, 2025). "The PREDIMED-Plus trial showed that adherence to a Mediterranean Diet supplemented with either nuts or extra virgin olive oil reduces hypertension and LDL-C levels, and improves insulin sensitivity and HDL levels, resulting in reduced cardiovascular events." (PMID 40077646, 2025). "The AdaBoost model was built using ALB, LDL-C, DM, total bilirubin, HbA1c, HDL-C, TG, creatinine, age, ALT, TC, BMI, fasting insulin, body weight, AST, PLT, uric acid, height, sex, and hypertension." (PMID 40361915, 2025). "Potential reasons for anatomical modifications in obese patients include the severity and duration of arterial hypertension, activation of the sympathetic nervous system, the RAAS, and the effects of growth factors, such as insulin." (PMID 40150180, 2025). "The survey indicated that women with primary education, being in a relationship, smoking, having hypertension, hypothyroidism and lipohypertrophy and being treated with multiple daily injections (MDI; automatic insulin pen) had high stress levels." (PMID 41040854, 2025). "Based on lab diagnostics and anthropometry: HbA1c, insulin, fasting glucose >6.1 mmol/L, HOMA index, lipid profile (TG >1.69 mmol/L, HDL-C <1.04 mmol/L), atherogenicity coefficient, BMI, WC >88 cm, hypertension >130/85 mm Hg." (PMID 41527607, 2025). "We also found that history of hypertension, ACEI/ARB use, insulin use and elevated Cr, BUN, and UA levels, which are often associated with kidney disease, were more common in the severely increased albuminuria group than in the other two groups." (PMID 39806776, 2025). "The RF model comprised ALT, DM, age, HDL-C, ALB, TG, fasting insulin, AST, LDL-C, creatinine, body weight, PLT, height, HbA1c, total bilirubin, hypertension, BMI, TC, uric acid, and sex." (PMID 40361915, 2025). "Insulin sensitivity, assessed using QUICKI, was also lower in both hypertensive groups—findings that are commonly observed in patients with hypertension." (PMID 40973781, 2025). "The GP model was constructed using the following variables: ALT, body weight, PLT, height, age, uric acid, creatinine, BMI, total bilirubin, AST, TG, ALB, fasting insulin, DM, HbA1c, LDL-C, TC, HDL-C, sex, and hypertension." (PMID 40361915, 2025). "For the linear SVM model, the selected variables were BMI, body weight, height, ALT, age, AST, creatinine, uric acid, fasting insulin, DM, HbA1c, PLT, hypertension, HDL-C, TC, TG, ALB, LDL-C, sex, and total bilirubin." (PMID 40361915, 2025). "The patient age, sex, BMI, SBP, DBP, smoking status, hypertension grade, glycaemia, Hb, HbA1c, HDL-C, LDL-C, TC, TG, uric acid, insulin use, and oral hypoglycaemic drug use were differed between the three groups (all P < 0.05)." (PMID 38218893, 2024).
Hypertension (continued). "Literature suggests that hypertension and MASLD share several common pathophysiological mechanisms, encompassing inflammation, SNS activation, and insulin resistance." (PMID 39337863, 2024). "In these analyses, a possible effect modification by sex was observed for age, hypertension, alcohol intake, heavy drinking, HOMA-IR, insulin and fruit intake (P for interaction < 0.20)." (PMID 38796541, 2024). "This might be because comorbidities like hypertension, cardiovascular disease, chronic obstructive pulmonary disease (COPD), asthma, surgery, trauma, psychiatric disorders, etc. may cause either dehydration or increase disturbance of the normal function of hormones, particularly insulin." (PMID 38468250, 2024). "Prevalence of hypertension, GMA, and glucose or insulin levels (as well as HOMA-IR), was higher in acromegalic patients." (PMID 37344722, 2024). "The baseline risk model included age, smoking, previous myocardial infarction, hypertension, previous stroke, SBP, DBP, HDL-C, eGFR, creatinine, uric acid, hs-CRP, HbA1c, LVEF, insulin, and oral hypoglycemic drugs." (PMID 38218893, 2024). "For example, long-term exercise in SHRs, beginning at the prehypertensive stage (four weeks old), improves vascular insulin sensitivity via down-regulation of vascular GRK2, which limits the progression of hypertension." (PMID 38961282, 2024). "Lastly, in our MVMR analysis, adjustments for confounders such as fasting insulin, HOMA-IR, high blood pressure, circulating CRP levels, and smoking were meticulously made." (PMID 38390197, 2024). "Meanwhile, depressed participants had higher levels of physical examination indexes (BMI and WC), sugar metabolism measurements (FPG, insulin and HOMA-IR), and the basic diseases (CVD, DM and hypertension) (p < 0.05)." (PMID 37032915, 2023). "No linkages between AAA diameter and bilirubin were found, also after adjusting to HDL cholesterol, triglycerides, hypertension, CAD, T2D, ACE, ARB, ASA, β-blockers, anticoagulation, diuretics, insulin, and T2D treatment." (PMID 37107322, 2023). "Previous studies comparing insulin detemir versus NPH in pregnancies with T1DM, T2DM, or GDM have shown comparable rates of hypertension." (PMID 37775682, 2023). "Studies have shown that insulin accelerates VSMC proliferation and migration, leading to the development of hypertension." (PMID 36479179, 2022). "Insulin and HOMA-IR parameters in normal, Level 1 MetS, or Level 2 MetS patients, and% hepatic steatosis (HS) and hypertension (HTN) in each group." (PMID 36160146, 2022). "Cardiovascular risk factors were also attenuated in the presence of a dietary approach to stop hypertension (DASH) pattern, decreasing the levels of fibrinogen, insulin, and diastolic blood pressure (DBP)." (PMID 35276919, 2022). "High levels of insulin also stimulate the renin-angiotensin-aldosterone system (RAAS) resulting in increased peripheral vascular resistance and hypertension." (PMID 36093171, 2022). "It is a clustering of interrelated metabolic disorders, which include insulin resistance, central obesity, hypertriglyceridemia, lowered HDL cholesterol concentration, and hypertension." (PMID 35453758, 2022). "Patients of both genders with Level 2 MetS had higher serum insulin and/or HOMA-IR values than Level 1, as well as a higher prevalence of hypertension and hepatic steatosis, being more pronounced among men." (PMID 36160146, 2022). "Out of the 696 patients 14% were smokers, 69% had pre- existing hypertension, 45% were on angiotensin converting enzyme inhibitor or angiotensin II receptor blockers (ACE-I/ARB), 33% were on home insulin and 51% were on metformin." (PMID 35725489, 2022). "The energy-restricted dietary regimens such as the Mediterranean diet, the Dietary Approaches to Stop Hypertension (DASH) diet, the plant-based diets were reported to ameliorate insulin sensitivity and reduce the incidence of T2D." (PMID 35369303, 2022).
Hypertension (continued). "The univariate logistic regression analysis showed that clinical factors including alcohol consumption, history of hypertension, BMI, DBP, PBG, 2 h insulin, 2 h C peptide, serum uric acid, eGFR, TC, TG, LDL-C and cathepsin S were possible risk factors of CVD." (PMID 33746900, 2021). "For this model, selected variables were hypertension, antihypertensive medicine, triglycerides, duration of IDDM, drinker, daily insulin dose, age, ACE inhibitors, BMI, HbA1c, and LDL." (PMID 34943504, 2021). "The vascular actions of insulin and IGF-1 have been found impaired in some cardiovascular disorders, such as hypertension and obesity." (PMID 34203897, 2021). "Future studies are recommended to confirm the roles of oxidative stress and antioxidants for insulin- and IGF-1-mediated cardiovascular dysfunction in the elderly population with hypertension." (PMID 34203897, 2021). "On the contrary, more women were taking oral hypoglycaemic agents and insulin, diuretics and CCB reflecting their higher prevalence of DM, hypertension and heart failure." (PMID 33556136, 2021). "Characteristics including age, sex, systolic BP (SBP), diastolic DP (DBP), BMI, TC, TG, LDL-C, HDL-C, WBC, FPG, fasting insulin, HbA1c, HOMA-IR, smoking, and medical history of hypertension, varied across the three age groups (P<0.05)." (PMID 34803930, 2021). "A number of clinically approved drugs indirectly reduce plasma PAI-1; these include insulin sensitizing agents for management of T2DM, such as metformin, and ACE inhibitors (used to treat hypertension)." (PMID 33937363, 2021). "Moreover, there are non-lipid factors that may increase CVD risk, such as hypertension, endothelial dysfunction, cardiac arrhythmia, oxidative stress, inflammation, thrombosis, the glucose-insulin axis, and the microbiome." (PMID 34362390, 2021). "The Hypertension group also showed significantly higher FBS (P < 0.001), HbA1c (P = 0.008), fasting insulin (P < 0.001), and HOMA-IR (P < 0.001) than the Normal BP group." (PMID 34347822, 2021). "It indicated that the greater decreases in NO production contributed to the worse impairments of endothelium-dependent vasorelaxation mediated by insulin and IGF-1 in the coexistence of aging and hypertension." (PMID 34203897, 2021). "After adjusting for age, hypertension, and other potential risk factors, OR for silent lacunar infarcts was significantly higher in 4 groups with either insulin sensitivity or muscle strength was not “High” compared with the group with High-insulin sensitivity and High-muscle strength." (PMID 34702849, 2021). "However, we did not include other cardiometabolic risk factors (such as high blood pressure, high fasting insulin levels) in the model which could also explain the association between liver enzymes and resting HR." (PMID 33959099, 2021). "Among them, a randomized double-blind placebo-controlled study in obese patients with well-treated hypertension documented a significant improvement of BMI, waist circumference, and LDL-c concentration along with an improvement of insulin sensitivity." (PMID 33218062, 2020). "The 4th quartile of changes in insulin, HOMA-IR, and IGR showed hazard ratios (95% confidence interval) of 1.31 (1.01–1.69), 1.18 (0.92–1.52), and 1.53 (1.18–1.98) for hypertension, respectively, in fully-adjusted models." (PMID 31728151, 2019). "In conclusion, the 12 weeks of PCA administration remarkably improved the endothelium-dependent vasorelaxation induced by insulin and IGF-1 in aging hypertension through enhancing the PI3K–NOS–NO pathway." (PMID 30934575, 2019). "In conclusion, our study demonstrated that 12 weeks of PCA administration remarkably improved the endothelium-dependent vasorelaxation induced by insulin and IGF-1 in aging hypertension through enhancing the PI3K–NOS–NO pathway." (PMID 30934575, 2019).
Hypertension (continued). "This study aimed to investigate the effects of PCA administration on vascular endothelial function, mediated by insulin and insulin-like growth factor-1 (IGF-1), and antioxidant activities in aging hypertension." (PMID 30934575, 2019). "Previous research has reported that the vascular actions of insulin and IGF-1 are pathologically altered and impaired in cardiovascular disorders, such as hypertension and obesity." (PMID 30934575, 2019). "This suggested that the aging hypertension evoked the decreased activation of PI3K and NOS, partly resulting in the impairments of NO production and insulin- and IGF-1-induced vasorelaxation." (PMID 30934575, 2019). "On pharmacological management, 31.3% of patients were on insulin therapy, 66.3% were given either ACEI or ARBs for management of hypertension and about 81.1% of patients were on statins." (PMID 31729951, 2019). "MS is defined as a group of IR markers, i.e., high blood pressure, impaired glucose metabolism, high serum triglyceride, and low serum High Density Lipoprotein (HDL), which result in triggering resistance to insulin-stimulated glucose uptake." (PMID 31121834, 2019). "The nutrition education intervention with dietary approaches to stop hypertension (DASH) performed significantly reduced FBS and serum insulin level of blood." (PMID 30788294, 2018). "Control and β GC-A KO mice showed similar weight gain, insulin sensitivity (ITT) and arterial hypertension under HFD." (PMID 30016962, 2018). "Being overweight or obese is the aggravating factor for hypertensive disorders, GDM (on insulin), emergency CS and low birthweight." (PMID 30115949, 2018). "The excessive level of circulating insulin, together with the increased level of FFA contributes to hypertension mechanisms, such as enhanced sodium reabsorption." (PMID 28282859, 2017). "DM2 duration, poor glycemic control (glycated hemoglobin; A1C >7%), SBP, increased heart rate, hypertension, CVD, and treatment with insulin showed a direct relationship with an increase in UACR levels." (PMID 26886129, 2016). "In animal models of hypertension and DM with evidence of nephropathy, AZL-M induced superior antihypertensive, insulin-sensitizing and anti-proteinuric effects as compared to olmesartan medoxomil." (PMID 27536242, 2016). "There were significant differences in age, BMI, SBP, DBP, FPG, PPG, insulin, HOMA-IR, triglyceride, HDL, ALT, AST levels, and the prevalence of female gender and hypertension among the three groups." (PMID 26621340, 2015). "We included age, fasting glucose, 2-hour glucose, fasting insulin, HOMA-IR, BMI, education, smoking, cardiovascular disease, hypertension, cholesterol, and physical activity as potential influencing factors of memory." (PMID 25798199, 2015). "HFC-fed minipigs exhibited IR through increased body weight, fasting blood glucose levels, plasma cholesterol and its composition, and insulin and free fatty acid (FFA) levels; decreased insulin sensitivity; impaired glucose tolerance; and hypertension." (PMID 25592139, 2015). "Total cholesterol, triglycerides, fasting glucose, insulin, glycated haemoglobin and blood pressure, have been examined before in SHROB rats and in the related SHRSP (stroke-prone spontaneously hypertensive rat) model, after supplementation with soybean oil." (PMID 25115868, 2014). "In order to control vascular microangiopathy in patients affected by IDDM with proteinuria and hypertension, we added aminaphtone to standard therapy for IDDM (insulin) and hypertension (angiotensin-converting enzyme inhibitors)." (PMID 25524258, 2014). "Plasma PTX3 remained statistically significant in association with BMI (P trend <0.001) and waist circumference (P trend <0.001) even after adjustment for age, sex, smoking, history of hypertension, triglycerides, HDL cholesterol, and insulin." (PMID 24705587, 2014).